TNF (tumor necrosis factor)
Diseases named in the same sentence as TNF in open-access papers (continued):
Sharing a sentence is not in itself a finding about the gene and the disease.
infection (continued). "In contrast, 4T1-upregulated Ccl7, Ccl12 and Ccl22 (most strongly upregulated by SFV/TNFα) were even more upregulated after infection." (PMID 40547518, 2025). "Previous studies have revealed that K. pneumoniae is capable of inducing a pro-inflammatory cytokine response in BMECs, as evidenced by the release of cytokines such as TNF-α, IL-1β, and IL-6, consistent with our results in a model of BMECs infection." (PMID 41206543, 2025). "IL-1β was produced by M2-like macrophages, dendritic cells, and neutrophils, whereas M1-like macrophages, which differentiated post-infection, produced IL-23, TNF-α, and IL-6, acting as initiators and amplifiers of the cytokine storm." (PMID 40127923, 2025). "Despite sharing regulatory functions with Tregs, DNTs also secrete cytokines (IL-4, IL-17, IFN-γ, and TNF-α) to exert T helper (Th)-like activities, exhibiting protective roles across infection models in mammals." (PMID 40821846, 2025). "Pre-incubation of THP-1 cells with HepEVs significantly reduced TNF-α, IL-1β, and IL-8 release post-NTHi infection." (PMID 41550953, 2025). "This prevents the production of important cytokines such as IL-1β, IL-6, IL-12, and TNF-α, thus limiting the body’s ability to fight infection." (PMID 41011796, 2025). "At 4 h post-infection, their expression remained undetectable, except for TNF-α, which reached approximately 2 pg/mL in reactivated-phases infections." (PMID 41450943, 2025). "For example, miR-146a plays an anti-infection role in THP-1 cells by negatively regulating secretion of TNF-α and IL-6." (PMID 40597229, 2025). "Following infection, all neonatal groups mounted significant increases in serum cytokines and chemokines, including G-CSF, GM-CSF, TNF-α, IL-6, MIP-1α, MIP-1β, and RANTES." (PMID 40766470, 2025). "Both doses significantly activated the transcription of STAT1 and its downstream interferon-stimulated genes, while high-dose infection additionally triggered a cytokine storm characterized by excessive IL-6 and TNF-α expression." (PMID 40941331, 2025). "Inflammatory cytokines including TNF‐α, IL‐15, IL‐23, and IL‐1β play a crucial role in the immune response to infections." (PMID 40539722, 2025). "In our study, in women with PCOS and confirmed infection with any atypical pathogen (n = 196), we analyzed the levels of proinflammatory cytokines, IL-1 β a, IL-6 and TNF-α." (PMID 40647668, 2025). "TNF-α has been documented to be involved in recruiting neutrophils to the site of infection, contributing to tissue destruction." (PMID 40732660, 2025). "Reporting of infections and infestations related to drug in treatment with TNF-α inhibitors with various indications." (PMID 40371340, 2025). "TNF-α is a pro-inflammatory cytokine produced by immune cells (e.g., macrophages and dendritic cells) in response to infection or tissue damage as a means of maintaining homeostasis." (PMID 41143415, 2025). "Using a murine ‘two-hit model’ combining CLP with secondary infection of P. aeruginosa, we observed immunosuppressive manifestations, such as reduced TNF-α and IL-6 secretion, elevated bacterial load, and increased mortality upon secondary insult." (PMID 41082631, 2025). "Concerning cellular immune response, levels of mice serum cytokines; IFN-γ, IL-15 and TNF-α were significantly higher (P < 0.001) after 10 and 21 days of infection as compared to healthy mice." (PMID 40029925, 2025). "The grass carp showed complex regulation of immune and metabolic responses during infection, especially activation of Toll-like receptors and TNF signaling pathways." (PMID 39858263, 2025). "The early secretory proteins CFP-10 and ESAT6 regulate macrophage apoptosis at various stages of infection by modulating TNF-α levels." (PMID 40429667, 2025). "For example, soluble TNF was critical for controlling primary infection with Listeria, while transmembrane TNF was sufficient to control secondary infection." (PMID 40279312, 2025).
infection (continued). "The clinical implications of this finding are not yet fully understood, but it highlights the need for further research into how anti-TNF-α therapy affects immune responses to parasitic antigens and potential infection risks in treated patients." (PMID 40872279, 2025). "The infection of macrophages by L. braziliensis induced a significant reduction in the production of TNF-α, which was reversed by CM in a concentration-dependent manner after 24 h of incubation with this test drug." (PMID 40299671, 2025). "Our study relies on real-world pharmacovigilance data and gave in-depth insights on AEs of infections and infestations in older adults following the usage of TNF-α inhibitors." (PMID 40371340, 2025). "Such factors include cytokines released during infection or inflammatory processes, such as interleukins-1 and 6 (IL-1 and IL-6), and tumor necrosis factor alpha (TNF-α) released in many inflammatory rheumatic diseases." (PMID 40723781, 2025). "Two days post-infection, the expression of TNF-α in BALF was significantly lower in the B. longum administration group than that of controls." (PMID 41035679, 2025). "The immune response to infection triggers the release of pro-inflammatory cytokines, such as tumor necrosis factor-alpha (TNF-α), interleukin-1β (IL-1β), and interleukin-6 (IL-6), leading to widespread tissue damage, capillary leakage, and hypoperfusion." (PMID 40429550, 2025). "Our multivariate logistic regression analysis revealed that elderly women were more vulnerable to infection when treated with TNF-α inhibitors." (PMID 40371340, 2025). "In contrast, a marked upregulation was observed in the brain and intestine, with the brain displaying peak TNFα expression on day 7 post-infection." (PMID 40723580, 2025). "TNF signaling enhances T-cell responses and regulates chemokine expression, crucial for immune cell recruitment and maintenance at the infection sites." (PMID 40738187, 2025). "Serum protein levels of IL-1β (B), TNF-α (C), and IL-6 (D) were examined through ELISA assays 24 hr post infection." (PMID 39998486, 2025). "Its protective effect was consistent with the drug-dependent decrease in IFN-β and TNF-α, confirming the improvement of infection outcomes through the dual pathways of “inhibiting bacterial invasion and reducing immunopathology”." (PMID 41301507, 2025). "Conversely, the PK-15-SOCS3 cells showed a substantial upregulation of IFN-β transcripts (*** p < 0.001) at 6, 12, and 48 hpi, while TNF-α expression was dramatically suppressed throughout the infection course (*** p < 0.001)." (PMID 40872795, 2025). "Early in the infection, corneal epithelial and resident immune cells rapidly release pro-inflammatory cytokines, such as IL-1β, TNF-α, and IFN-γ, increasing vascular permeability and recruiting additional immune cells to the site." (PMID 39861857, 2025). "Pro-inflammatory factors, such as IL-1β, IL-6, and TNF-α, can mediate host’s inflammatory response by rapidly generating an immune response after pathogen infection." (PMID 40821810, 2025). "The decline in TNF-α levels in the early days of infection by the HY/HA-ΔL226/R229I strain correlates with an increase in viral titers." (PMID 40338080, 2025). "As a result, infection-upregulated genes were expressed at higher levels in the SFV/TNFα group (Cluster 1) and in the SFV/IFNγ group (Cluster 3)." (PMID 40547518, 2025). "Mincle deficiency significantly reduced 18:1-EG-induced production of MIP-2 and TNF-α in mouse BMDCs and increased CFUs in mouse lungs during early infection, indicating that the 18:1-EG-mediated immune response depends on Mincle." (PMID 40273119, 2025). "Initially, the immune response focused on combating the infection, evidenced by strong correlations among inflammatory cytokines like IL-1β, IL-6, IL-8, TNFα, and IFNγ." (PMID 40557167, 2025).
infection (continued). "Tocilizumab effectively induces remission in GCA patients, while abatacept and TNF inhibitors offer minimal benefits with increased infection risks, according to this meta-analysis." (PMID 40546904, 2025). "Consistent with a previous study, VR-2332 infection upregulated TNF-α transcript expression in PAM-KNU cells more potently than the field isolates." (PMID 40302751, 2025). "In the early stages of infection, innate cytokines such as IL-1, IL-6, and TNF- α induce CRH secretion by neurons in the paraventricular nucleus (PVN) of the hypothalamus." (PMID 40176892, 2025). "In the present study, the mRNA expression of IL-1β and TNF-α was upregulated in the brain of CLEC12A−/− mice upon infection." (PMID 41214106, 2025). "WT and CASP4-/- cells also released similar levels of the inflammasome-independent cytokine TNF-α upon infection with WT Salmonella at 24 hpi." (PMID 40162563, 2025). "TNF-α is a central mediator of inflammation and immune cell activation, and triggers an inflammatory response at the site of infection." (PMID 41187212, 2025). "In summary, TNF, IL-8, and IL-10 specifically increased following infection, whereas CCL2 and IL-18 showed an infection-dependent reduction." (PMID 40794782, 2025). "Injury and infection activate immune cells, release inflammatory mediators (e.g., TNF‐α, IL‐1β), affecting the excitability of nerve fibers, promoting pain signal generation." (PMID 41395451, 2025). "Upon infection, these mice demonstrated a lower Th1 cytokine response (TNF-α and IFN-γ) and reduced CD4+ and CD8+ T cell production." (PMID 40435099, 2025). "Consistent with macrophage infection, apoptotic caspase activation in TNF-primed CMT-93 cells was diminished following Nec-1s treatment or ΔnleE infection." (PMID 40128366, 2025). "And the ITA infection group showed more significant upregulation of cytokines (IL-4, IL-10, TNF-α, IFN-γ), histopathological damage to lungs, and higher bacterial load and mortality than the IN and ITI groups." (PMID 40723822, 2025). "Among the different infection types, the five TNF-α inhibitors had the strongest signal in mycobacterial infectious disorders and the weakest signal in fungal infectious disorders." (PMID 40371340, 2025). "In our previous study, the capacity to overproduce TNF-α in serum and promptly establish infection played critical roles in the sudden death of infected mice during the early phase of infection." (PMID 40574283, 2025). "The tissue model mounted a strong inflammatory response to STm infection, as evidenced by the secretion of IL‐1β and TNF, while the anti‐inflammatory cytokine IL‐10 was also detected." (PMID 39807570, 2025). "Apoptotic markers (caspase-3, Bax, Bcl-2) were analyzed by immunofluorescence and immune genes expression kinetics (TLR3/7, RIGI, MDA5, IL-1β, IL-6, TNFα, IL-10, IFNβ and β-catenin) were measured at defined time points post-infection by RT-qPCR." (PMID 41157617, 2025). "Serum levels of TNF-α, IL-6, and IFN-γ are elevated in DFI patients and are closely associated with infection severity and prognosis." (PMID 40677522, 2025). "In vitro infection models demonstrated that SA reduced TNF-α and IL-6 expression in CHIKV-infected 293T cells and increased the survival rate of infected BHK-21 and 293T cells by ~25%." (PMID 39917312, 2025). "Other researchers have demonstrated that elevated levels of specific inflammatory markers present during the acute phase of infection—namely, CRP, IL-6, and tumor necrosis factor (TNF)—are correlated with an increased risk of developing long COVID." (PMID 41302639, 2025). "It was also described that infection with the same strain triggered an increase in circulating levels of TNF-α." (PMID 41150385, 2025). "Infection with 103 TCID50 of PRV-GXLB-2013 resulted in significantly elevated levels of TNF-α, IL-1β, IL-6, IL-8, and MLKL in brain tissues, serum, and C8-D1A cells, compared to the control group (p < 0.01)." (PMID 40732040, 2025).
infection (continued). "After infection, intracellular TNF was readily detected in both neutrophils and Ly6C+ monocytic cells in the spleen and liver after 1 day and 7 days post-infection, respectively." (PMID 40064845, 2025). "In turn, this perturbs the nuclear relocalization of transcription factors to the nucleus in response to infections, thereby reducing the production of pro-inflammatory cytokines (TNF-α and IL-8) and attenuating the host immune response." (PMID 41011796, 2025). "In TB, TNF-α plays a dual role and is essential for macrophage activation to control infection and granuloma formation." (PMID 40310305, 2025). "K. pneumoniae infection triggered transcriptional upregulation of IL-1β, IL-6, IL-8, and TNF-α within 2 h post-infection, preceding significant changes in ferroptosis markers." (PMID 41343264, 2025). "Tumor necrosis factor-α (TNF-α) is a proinflammatory cytokine that is released by activated macrophages, T cells, and endothelial cells in response to infection, tissue injury, and inflammation." (PMID 40278353, 2025). "KEGG analysis reveals DE‐PRGs enrichment in pathways related to NF‐kappa B signaling, apoptosis, infection, and TNF signaling." (PMID 39854144, 2025). "They demonstrated that Omp25 from this bacterium inhibits TNF-α production during the infection of human THP-1 macrophages." (PMID 40606156, 2025). "The infection (or nerve injury)-prompted excessive release of pro-inflammatory cytokines such as TNF-α initiates pain." (PMID 40430212, 2025). "CRP is produced as a response to an infection or trauma, upregulated by cytokines, especially IL-6, but also IL-1 and TNF." (PMID 41007875, 2025). "Analysis of the pulmonary transcriptional levels of Monocyte chemoattractant protein-1 (MCP-1), IL-6, and TNF-α revealed that their expression was highest at 12 hpi following infection with both the HY037 and HY041T strains." (PMID 41274864, 2025). "We previously reported that the infection induced TNF-α, IL-17A, and IL-1β expression, which potentially activates the NF-κB signaling pathway." (PMID 40127923, 2025). "TNF-α, IL-6, IL-8, and IL-1β showed higher levels in prolonged infection of HAO with rHPh-TX H5N1-Venus vs. pH1N1-mCherry." (PMID 40712003, 2025). "After vPdR-36U infection, the TNF signaling pathway and platelet activation pathway were upregulated." (PMID 40006915, 2025). "Consistently, Yptb ΔtkeA infection led to a decreased Tnfa expression and TNFα secretion in PMs compared to WT strain infection." (PMID 40365777, 2025). "Consistent with the bone measurement results, indole supplementation during ΔtnaA infection significantly elevated IL-1β, IL-6, and TNF-α levels in the gingival tissue of the Mutant + Indole group compared to the Mutant group." (PMID 40011497, 2025). "Analysis revealed that TNF-α and IL-1β, important pro-inflammatory cytokines, gradually increased on different days post-infection (1, 3, 7, 15 dpi), peaking at 7 dpi." (PMID 39799330, 2025). "The downregulation of MUC2 during infection is driven by parasite-induced epithelial stress, pro-inflammatory cytokines (as TNF-α and IFN-γ), and oxidative damage, which impair goblet cell function and mucin gene transcription." (PMID 41479898, 2025). "Activated innate cells phagocytose Candida and release pro-inflammatory cytokines (IL-1, TNF-α, IL-6) that help recruit more immune cells to the site of infection." (PMID 40586608, 2025). "The main result of the MyD88-dependent pathway is the rapid induction of pro-inflammatory cytokines (e.g., TNF-α, IL-6, IL-12), which play a vital role in the immune response to infections." (PMID 40284971, 2025). "The initial response of DCs to CPXV infection involves the secretion of inflammatory cytokines such as TNF-α and IL-6, which facilitate the recruitment of other immune cells to the site of infection." (PMID 40872644, 2025). "Since our transcriptomic analysis also revealed increased TNF expression upon infection (log2 fold change = 3.7, adj." (PMID 40249190, 2025).
infection (continued). "IL-6, TNF-α, IL-10 and other cytokines are important participating factors in the infection related cytokine storm." (PMID 40538651, 2025). "Following infection with Eimeria, TNF-α levels rose significantly, reaching an average of 188.23 ± 10.01 pg/ml." (PMID 41479898, 2025). "TNF-alpha is elevated during pathogen infection or chronic inflammation mediated by various stresses such as heat stress." (PMID 41295269, 2025). "Instead, TNF priming was required to promote caspase-3/7 activity, with apoptotic caspase cleavage detectable from 5 h post-infection." (PMID 40128366, 2025). "In the early days post-infection, innate immunity predominates, characterized by increased levels of inflammatory cytokines (e.g., IL-6 and TNF-α) in response to initial viral replication." (PMID 41357245, 2025). "The production of pro‐inflammatory cytokines such as IL‐6 and tumor necrosis factor (TNF)‐α helps recruit immune cells to the site of infection, promoting the clearance of the virus." (PMID 39912556, 2025). "In comparison with NI controls, TNF concentrations in serum were increased in infected mice, at 120 dpi (pre-therapy), and even higher as infection progressed (Veh, post-therapy)." (PMID 41237192, 2025). "Solid organ transplantation, tumor necrosis factor-alpha inhibitors, and anti-CD52 agents have also been reported to increase the risk of clinical infection." (PMID 40801539, 2025). "Serum protein levels of IL-1β (L), TNF-α (M), and IL-6 (N) were examined through ELISA assays 24 hr post infection." (PMID 39998486, 2025). "According to the descriptive analysis, females (73.06%) made up the majority of TNF-α inhibitor-related infections and infestations." (PMID 40371340, 2025). "This situation leads to an increased parasite burden and pathogenesis, as previously observed in our anti-TNF immunosuppressed mice at six weeks post-infection." (PMID 40808943, 2025). "such as interleukin-6 (IL-6) and tumor necrosis factor-alpha (TNF-α), are essential in the initial response to infection, injury, or exercise." (PMID 40402402, 2025). "Endogenous levels of NFκB regulate transcription in response to the stress stimulus including those from tumor necrosis factor alpha (TNFα), reactive oxygen species, inflammatory factors and infection." (PMID 41459064, 2025). "More specifically, studies in mice show that pulmonary Mab infection drives the activation of T-helper 1 (Th1) cells that are characterized by the simultaneous production of both IFNγ and TNF." (PMID 40415550, 2025). "Infection with G. parasuis elicits a pronounced inflammatory response, characterised by elevated levels of IL-1β, IL-6, TNF-α, and IL-17, which collectively contribute to tissue damage and systemic inflammation." (PMID 40665414, 2025). "While IL-1β, IL-6, and TNF-α levels were similar at admission, IL-1β and TNF-α significantly increased during follow-up, indicating immune activation in later infection stages." (PMID 40611327, 2025). "It has been reported that S. negevensis infection inhibits apoptosis induced by TNFα (extrinsic pathway) or STS (intrinsic pathway) at day 3 post-infection; this effect depends on the MOI and is acquired faster when more bacteria are present." (PMID 41204030, 2025). "They secrete inflammatory cytokines such as tumor necrosis factor‐alpha (TNF‐α), interleukin‐1 (IL‐1), and interleukin‐6 (IL‐6) to enhance the inflammatory reaction and attract more immune cells to the site of infection." (PMID 40539722, 2025). "Previously, we showed how BEV triggers elevated levels of TNF-α in the early stages of infection and expression of TNF-α is negatively correlated with the virus replication or virus titre." (PMID 39956903, 2025). "The study found that polymorphisms in the TLR4 gene (rs4986790), IL-10 gene (rs1800896), TNF-α gene (rs1800629), and MBL2 gene (rs1800450) were significantly associated with patients’ susceptibility to infection, disease severity, and prognosis." (PMID 40692949, 2025).